HIF1A (hypoxia inducible factor 1 subunit alpha)
Diseases named in the same sentence as HIF1A in open-access papers (continued):
Sharing a sentence is not in itself a finding about the gene and the disease.
cancer (continued). "In this meta-analysis, we investigated the association between the HIF-1α 1772 C/T and 1790 G/A polymorphism and cancer risk." (PMID 20035632, 2009). "A number of investigators have studied the possible association between the HIF-1α polymorphisms and cancer risk, but the results have been conflicting." (PMID 20035632, 2009). "The results from the published studies on the association between hypoxia-inducible factor -1α (HIF-1α) polymorphisms and cancer risk are conflicting." (PMID 20035632, 2009). "It has been previously reported that impaired SDH activity in several cancer types is associated to HIF-1α stabilization, through a mechanism involving intra-cytoplasmic succinate accumulation and consequential PHD2 inhibition." (PMID 19587783, 2009). "In this paper, a meta-analysis was performed on previous reports to investigate the association of HIF-1α 1772 C/T and 1790 G/A polymorphism with cancer." (PMID 20035632, 2009). "Recent studies have shown that HIF-1α is increased in various carcinomas and its presence is associated with poor prognosis and resistance to therapy." (PMID 19919679, 2009). "HIF-1α is the relevant, oxygen-dependent subunit and its overexpression has been associated with a poor prognosis in a variety of malignant tumours." (PMID 16035955, 2005). "A recent report demonstrates that human common cancer cells over-express hypoxia-inducible factor-1α (HIF-1α) in vivo and that the expression of HIF-1α is associated with metastasis." (PMID 12085186, 2002). "We systematically examine how TME components: hypoxia (HIF-1α pathway), acidosis, cancer-associated fibroblasts (TGF-β/PDGF signaling), and immune cells (NF-κB-mediated immunosuppression) activate signaling cascades that directly interface with epigenetic machinery." (PMID 42082974, 2026). "Notably, we show that circIST1 drives HIF‐1α‐mediated aerobic glycolysis—a metabolic hallmark of cancer—‐by enhancing glucose uptake, lactate production, and glycolytic flux." (PMID 41541658, 2026). "This study uncovered that tramadol impaired cancer cell viability through two mechanistically linked but separate processes: the stabilization of HIF-1α under normal oxygen conditions and the activation of paraptotic cell death driven by oxidative stress and ER dysfunction." (PMID 41526224, 2026). "Furthermore, treatment with LM to cancer cells for 24 h led to upregulation of HIF‐1α and genes associated with cell proliferation and survival, suggesting an acceleration of cancer progression." (PMID 41160815, 2026). "The hypoxic microenvironment resulting from the rapid oxygen consumption of rapidly dividing cancer cells causes the accumulation of hypoxia-inducible factor-1α (HIF-1α) due to reduced catalytic activity of prolyl hydroxylase domain 2 (PHD2) and Von Hippel-Lindau (VHL)." (PMID 41614951, 2026). "A review study that analyzed 97 association studies identified links between 16 HIF1A SNPs and 40 disease phenotypes, including 14 types of cancer, such as breast cancer, lung cancer, colorectal cancer, stomach cancer, prostate cancer, oral cavity cancer, and renal cell carcinoma." (PMID 40959922, 2025). "Moreover, low oxygen and HIF-1α can cause cancer cells to transform into cancer stem cells (CSCs) as a survival strategy in low-oxygen settings." (PMID 41305000, 2025). "HIF-1α has been linked, in a recent study, to the development of chemotherapeutic resistance in cancer; consequently, cisplatin resistance may be reversed by targeting HIF-1α using RNA-interference or small interfering RNA." (PMID 40728967, 2025). "CA9, another downstream gene of HIF1A, is well‐known for its association with various cancers." (PMID 40417738, 2025). "HIF1A is recognized as a biomarker linked to cancer aggressiveness in OSA." (PMID 40948653, 2025). "These discrepancies suggest that the impact of HIF1A polymorphisms on patient survival may be cancer-type or treatment specific." (PMID 40959922, 2025).
cancer (continued). "Additionally, it is one of the few studies examining HIF1A polymorphisms in cancer within a European population, as most previous studies has been conducted in Asian populations." (PMID 40959922, 2025). "This assumption is based on the data on inhibition of HIF1α-oxidizing prolyl hydroxylases by fumarate or succinate in cancer cells with a deficiency of fumarate hydratase and/or succinate dehydrogenase, which results in pseudohypoxia even with normal oxygen content in the medium." (PMID 40071074, 2025). "Tissue-specific TSGA10 expression further modulates cancer susceptibility: high levels in the testes and brain may protect against thermal and oxidative damage, whereas low expression in the liver permits HIF-1α-driven metabolic plasticity." (PMID 40507237, 2025). "Nevertheless, our findings may contribute to understanding the role of HIF1A polymorphisms in MM and cancer more broadly, but further studies will be necessary to clarify their role." (PMID 40959922, 2025). "HIF‐1α methylation is also implicated in its stability and the progression of human cancer." (PMID 40227962, 2025). "Their findings revealed a HIF-1α/IL-1β signalling loop between cancer cells and tumour-associated macrophages in a hypoxic microenvironment, leading to epithelial–mesenchymal transition and cancer cell metastasis." (PMID 40264757, 2025). "Thus, in cancer patients, the expression of HIF-1α is closely linked to the development of many aspects of cancer cell growth, energy metabolism, and metastasis." (PMID 41585262, 2025). "The findings of this study have improved our understanding of the role of HIF1A polymorphisms in MM and may offer valuable insights into their impact on other cancers as well." (PMID 40959922, 2025). "Notably, HIF-1α can upregulate the expression of PD-L1, a factor implicated in immune evasion within the cancer niches." (PMID 39744225, 2025). "Moreover, studies have shown that HIF1A polymorphisms are associated with the risk of developing various cancers." (PMID 40959922, 2025). "Instead, choline metabolism in cancer and glycerophospholipid metabolism were significantly activated, leading to increased choline consumption and phosphatidylcholine accumulation, which was associated with elevated levels of HIF-1α." (PMID 40159598, 2025). "In this regard, HIF-1α may activate lipolysis in perirenal adipocytes in the hypoxic microenvironment, HIF-1α decreased expression being demonstrated to be associated with a limited access of cancer cells to adipose-derived lipids." (PMID 40227577, 2025). "Furthermore, it has been found that in various types of cancers, the development of resistance to chemo and radiotherapy is associated with overexpression of the HIF-1α." (PMID 38313904, 2024). "Additionally, HIF-1α is up-regulated in many forms of cancer and is associated with cancer pathogenesis." (PMID 39684225, 2024). "However, in certain malignancies, elevated HIF-1α levels are associated with lower cancer stage or decreased patient mortality, highlighting context-dependent functions for HIF-1α27." (PMID 39227650, 2024). "HIF-1α is responsible for activating genes associated with angiogenesis, cell growth and survival, invasion and metastasis, glucose metabolism, immune system evasion, and resistance to several cancer therapies." (PMID 38799423, 2024). "Moreover, we observed that VM formation in EBV-associated epithelial cancers dependent on the HIF-1α mediated crosstalk between cancer cells and M2c-like macrophages." (PMID 39267775, 2024). "Additionally, SPP1 (also known as osteopontin/secreted phosphoprotein 1) secreted by M2 macrophages (step 5) can modulate HIF-1α (step 6), and is associated with hypoxia and cancer metastases." (PMID 38535967, 2024). "In the case of PDT, the survival of cancer cells may be associated with NF-kB, hypoxia-inducible factor 1-alpha, B-cell lymphoma family proteins (HIF-1α and Bcl-2, respectively) and mitochondrial HSP-60244–248." (PMID 39138299, 2024).
cancer (continued). "Disturbance due to I21N‐mediated structural modification in the binding capacity between SSAT1 and HIF1α could also lead to pathogenic state, for example, cancer." (PMID 39041636, 2024). "Hypoxia induces the formation of hypoxia-inducible factor 1-alpha (HIF1α), leading to the activation of cancer-associated fibroblasts, with the release of transcription growth factor-beta (TGFβ) and other chemokines leading to the upregulation of cell diversity within the TME." (PMID 38611081, 2024). "In this meta-analysis, the association between cancer stage progression and positive HIF1A protein expression may support HIF1A-related EMT." (PMID 38877062, 2024). "HIF1α, a key transcription factor in cellular responses to hypoxia, has been implicated in cancer." (PMID 38769340, 2024). "Another important function of HIF1α is that it is involved in mediating the expression of multiple immunosuppressive molecules, which are associated with the cancer cells’ development, progression, and metastasis, and possibly ignite the EMT in a TGF-β-dependent manner." (PMID 38361941, 2024). "Concerningly for carriers higher fimbrial HIF-1α may also reflect synergy with BRCA1 loss as a potential cancer-driving mechanism." (PMID 38539519, 2024). "Furthermore, using multiple molecular approaches, an interesting investigation revealed that RON directly regulates HIF-1α overexpression, the latter of which is a key determinant steering the genes associated with the spread of cancer cells." (PMID 38904016, 2024). "Although the role of hypoxia/HIF-1α signaling in EMT remains unclear in PCa, HIF-1α signaling has been implicated to induce EMT in other cancers." (PMID 38792011, 2024). "In addition, hypoxia-inducible factor 1α (HIF-1α), a pivotal hallmark of hypoxia, is highly overexpressed in a variety of cancers and contributes to the aggressive and metastatic phenotype of tumors." (PMID 37087475, 2023). "Interestingly, in NOX4 knockout cancer cells, the expression of HIF1α-targeting genes, such as SLC2A1, encoding a glucose transporter, is prevented, thereby supporting the relevant role of NOX4-mediated metabolic reprogramming." (PMID 36768405, 2023). "However, research on cancer characteristics linked to HIF-1α in chronic hypoxia remains limited, underscoring the need for further investigation." (PMID 37777750, 2023). "Moreover, several lncRNAs contribute to metabolic reprogramming in cancer cells, mainly due to post-translational modifications of key metabolic players, such as HIF-1α and the c-Myc oncogene, as well as other cancer-associated proteins and pathways." (PMID 37444595, 2023). "ROS can also stabilize HIF1a, and cause cancer metastasis and drug resistance." (PMID 37790761, 2023). "Elevated expression of HIF-1-α and hnRNP A18 is associated with poorer cancer patient prognosis." (PMID 36539586, 2023). "To trigger the similar Warburg effect with aerobic glycolysis of cancer cells in yeast, we integrated an expression cassette containing HIF-1α and ARNT genes, encoding the two subunits of HIF-1 complex, into the yeast chromosome of strain BY4741, deriving the strain XN01." (PMID 39883335, 2023). "As a close connection between VEGF signaling pathway and Hypoxia in cancer development, Hypoxia-related genes were also compared between high-risk and low-risk samples, and it is certain that HIF1A expression was significantly higher in high-risk samples than in low-risk samples." (PMID 38044951, 2023). "Therefore, understanding the mechanism underlying HIF-1a regulation under hypoxic conditions is key to developing new strategies for cancer treatment." (PMID 37821935, 2023). "Notably, the anticancer effects of AsA are not limited to HIF-1α suppression; AsA contributes to glycolysis attenuation in cancer cells, causing DNA damage via reactive oxygen species due to redox imbalance." (PMID 38012636, 2023).
cancer (continued). "Interestingly, the MAOA/HIF1α signaling pathway was later found to be responsible for EMT induced by cancer-associated fibroblasts in PC as well." (PMID 36860320, 2023). "Moreover, FBXW7 can target hypoxia-inducible factor-1α (HIF-1α) for ubiquitin-dependent degradation during hypoxia, which causes metabolic changes and angiogenesis in cancer cells." (PMID 37176148, 2023). "Moreover, HIF-1α plays a pivotal role in cancer onset, development, progression and its association with resistance in BC and other pathologies has been molecularly elucidated." (PMID 37407979, 2023). "Loss of HIF1A can also increase cancer cell proliferation, invasion, and metastasis activity." (PMID 36639776, 2023). "Hypoxia-inducible factor 1 subunit alpha (HIF1A) is very important for the progression of cancer since regions of hypoxia are commonly associated with rapidly growing solid tumors as they outgrow their blood supply, and the response to this O2 starvation is the stabilization of HIF1A." (PMID 37228120, 2023). "Notably, increased levels of HIF-1α have been associated with a worse prognosis in many types of cancer, including OPSCC." (PMID 37046615, 2023). "Finally, we analyzed the levels of the hypoxia inducible factor 1α (HIF-1α), a transcription factor that regulates the expression of genes implicated in glycolysis and plays a key role in cancer metabolism reprogramming, in both control and mutant cells." (PMID 36674816, 2023). "Therefore, in this paper, we performed a statistical meta-analysis to draw a consensus decision about the association of HIF1A gene polymorphisms with several diseases except cancers giving the weight on large sample size." (PMID 35972942, 2022). "In addition to the link between high viperin expression and worse patient outcomes, both hypoxia/HIF-1α and CSCs have been implicated in resistance to chemotherapy, which leads to cancer progression or recurrence." (PMID 36519538, 2022). "Several studies have proven that HIF-1α/PKM2 pathway-associated metabolic changes may facilitate apoptosis resistance in cancer cells." (PMID 35571239, 2022). "Indeed, high HIF-1α levels have been associated with the overexpression of both GFs and GFRs in human cancers." (PMID 35158804, 2022). "The transcription factor HIF-1α orchestrates the expression of a vast number of essential cellular functions in genes, affecting cancer progression associated with angiogenesis (as VEGF), metabolism (hexokinase, glucose transporters), cell survival, and proliferation (TGF-α, C-Myc)." (PMID 36185255, 2022). "Thus, HIF-1α expression in many common human cancers is associated with increased patient mortality." (PMID 35406562, 2022). "However, fumarate is a formidable suppressor of 2-OGDD enzymes, so it can also retain the pseudohypoxic conditions that describe FH-deficient cancer cells by stabilizing HIF1α during normoxia by inhibiting the activity of PHD enzymes." (PMID 35847841, 2022). "Furthermore, HIF-1α was also found to be significantly upregulated in various human cancers and strongly associated with poor prognosis." (PMID 36124026, 2022). "Inspired by this concept, we developed a 5-ALA and CAT co-delivery system based on a theranostic microneedle patch (MN-CCPCA) that forces cancer cell to release the false signal of a “heme deficiency” and thus shuts down the outflow of PpIX through the cascaded downregulation of HIF-1α and FECH." (PMID 36266306, 2022). "Furthermore, co-expression of iNOS with COX-2 or HIF-1α is extensively reported in histological studies and associates with poor prognosis in several types of cancer." (PMID 35660630, 2022).
cancer (continued). "In particular, the highly hypoxic muscle-invasive bladder cancer (MIBC) overexpresses the cancer-associated carbohydrate antigen sialyl-Tn (STn), which has been reported to be at least in part due to a HIF-1α-dependent cell survival strategy that favors cell migration and invasion." (PMID 35211123, 2022). "YAP1 could regulate multiple genes involved in angiogenesis through E2F1; it also associates with HIF1α in cancer cells under hypoxic conditions, inducing the VEGF-A promoter." (PMID 35937460, 2022). "We found a positive association between KDM6B and HIF1α in various cancer types." (PMID 35186918, 2022). "HIF-1α has been associated with chemotherapy failure in various cancers." (PMID 36326232, 2022). "HIF1α accumulation is implicated in the development of malignant tumors." (PMID 35287356, 2022). "HIF-1α signaling activated in hypoxia conditions contributes to cell biology associated with oncogenesis, a key issue restraining the chemotherapy efficiency in various cancer treatment including CC." (PMID 35310917, 2022). "Keap1-NRF2 activation is associated with HIF1α upregulation in selected cancer types." (PMID 36009198, 2022). "Therefore, stabilization of HIF-1α is associated with poor prognosis and higher rates of mortality in different cancers." (PMID 36079025, 2022). "Besides, pharmacological inhibition of HIF-1α enhances the anti-cancer potency of oxaliplatin, demonstrating the association of hypoxia with oxaliplatin resistance." (PMID 34575983, 2021). "Finally, we demonstrate that pH and stiffness modulate the expression of two master regulators in cancer, yes-associated protein (YAP) and hypoxia inducible factor 1 (HIF-1A), suggesting an interplay between cancer metabolism and mechanotransduction." (PMID 34209094, 2021). "In addition, HIF-1α is associated with the expression of Slug in various cancers presumably because the promoter of the SNAI2 gene contains an HIF-1α response element where HIF-1α binds to and acts as a transcription factor." (PMID 34829545, 2021). "The SOX9 and HIF-1α cause hypoxia and reduce anti-cancer drug delivery in the tumor region." (PMID 34262595, 2021). "In human cancers, intra tumoral hypoxia causes overexpression of HIF-1α." (PMID 34715860, 2021). "Importantly, high HIF-1α levels and, to some extent, high Gal3 expression are associated with a poorer survival of human cancer patients, in particular in association with mutant KRAS, which emphasizes the need for suitable potent inhibitors." (PMID 33672199, 2021). "In addition, HIF-1A is overexpressed in many cancers and its overexpression is often positively associated with poor prognosis 16-18." (PMID 33403040, 2021). "Additionally, strong patterns of pyknotic apoptosis, as well as downregulation of proliferative‐associated proteins (Ki67, CD31, and HIF‐1α), were observed in histopathological and immunohistochemical patterns of treated mouse malignant tumors, respectively." (PMID 34626092, 2021). "In addition, the partial reduction in the oxygen pressure leads to the activation of hypoxia-inducible factor 1 alpha (HIF-1α) in both cancer cells and cancer-associated fibroblasts (CAFs)." (PMID 34685596, 2021). "However, it remains to be investigated the mechanism(s) underlying how cancer cells response to hypoxic conditions through HIF-1α-mediated transcriptional regulation." (PMID 34336836, 2021). "Missense mutations within the bHLH and PAS domains of Hif-1α/Hif-2α proteins have been linked to pathogenesis of various cancers, such as stomach adenocarcinomas, endometrial carcinomas, brain gliomas, lung adenocarcinomas, hepatocellular carcinomas and skin melanomas." (PMID 33799876, 2021). "Our data demonstrated that sevoflurane and desflurane, commonly used for surgical anaesthesia, may contribute to the risk of cancer recurrence after surgery that may be involved with the HIF-1α signalling pathway via miRNA mediation." (PMID 33673181, 2021).